EGFR (epidermal growth factor receptor)
Diseases named in the same sentence as EGFR in open-access papers (continued):
Sharing a sentence is not in itself a finding about the gene and the disease.
cancer (continued). "In the third study, plasma samples collected from first-line EGFR-TKI-resistant patients (n = 21) were genotyped by Sel-Cap and NGS cancer panel." (PMID 33266057, 2020). "For example, in urologic cancer, common genes regulated by prognosis-alternative miRNAs such as BCL2, EGFR, KIT, PDGFRA, and VEGFA, have been validated as anti-cancer drug targets previously." (PMID 32523951, 2020). "Various EGFR-and ERBB2-CAR-T clinical trials are also under evaluation for patients with various cancer types (ClinicalTrials.gov Identifier: NCT03618381, NCT03638167, NCT03696030, NCT03198052, etc.)." (PMID 32708604, 2020). "Various oncogenic pathways have been reported to affect expression of MHC-I, β2M, and other APM components in cancer, including the MAPK-, epidermal growth factor receptor (EGFR), HER2, c-MYC, and n-MYC pathway." (PMID 32630675, 2020). "In this work, we used single-molecule super-resolution microscopy to visualize single receptor clusters of EGFR and MET in two cancer cell lines." (PMID 32316583, 2020). "Long-term exposure to NNK combined with arecoline activated EGFR/AKT signaling is involved in antiapoptosis, cancer stem cell properties, and cisplatin resistance in head and neck SCC (HNSCC) cells." (PMID 31956359, 2020). "Tyrosine kinase inhibitors (TKIs) generally target proteins in the epidermal growth factor receptor (EGFR) family and have been developed as a cancer therapy that prevents growth factor signaling in various cancer models." (PMID 32528877, 2020). "We previously developed a PIC system that comprises of the U.S. Food and Drug Administration (FDA)-approved anti-EGFR monoclonal antibody cetuximab (Cet) and a clinically used benzoporphyrin derivative (BPD) photosensitizer to target cancer cells." (PMID 31898555, 2020). "Development of mTOR-dependent vulnerability in both Kras- and EGFR-mutant LUAD cells suggests that this phenotype could be a prevailing characteristic of chemotherapy-relapsed LUAD or MAPK-driven cancers in general, irrespective of the underlying pathway mutation." (PMID 32943635, 2020). "All anti-cancer activities are given by activation or inhibition of pathways such as HDAC1/PTEN/Akt, EGFR/ErbB2/ErbB3, and PI3K/Akt; PI3K-AK-mTOR, HDAC1/PTEN/Akt; Wnt/β-catenin." (PMID 32923398, 2020). "In HCC, lnc-EGFR promotes Treg differentiation, CTL inhibition and cancer progression in an EGFR-dependent manner." (PMID 33148302, 2020). "We previously reported that activation of FCHSD2 by ERK1/2 phosphorylation increases the rate of TfnR and EGFR internalization by CME and suppresses signaling from cell surface EGFRs, specifically in cancer cells." (PMID 32678845, 2020). "At the same time, these target protein genes are involved in a variety of cancer pathways, indicating that parthenolide exhibits potent anticancer activity against NSCLC by targeting EGFR signaling." (PMID 33292235, 2020). "The enzymatically inactive mutant exhibits cancer in two-step process: in the first phase, it disturbs the interaction of HER2 with other receptors in this family (EGFR, ErbB3) as well as other tyrosine kinase receptors (MET, IGF-1R)." (PMID 32824561, 2020). "Selatinib ditosilate, an oral, reversible, dual inhibitor of epidermal growth factor receptor (EGFR) and ErbB2 tyrosine kinase receptors, has recently entered clinical development as a potential therapeutic agent for cancer." (PMID 32535812, 2020). "Thus, changes in EGFR or ROS signaling in the absence of TKS4 might cause these cancer cells to shift into EMT." (PMID 33143131, 2020). "This binding resulted in the expression of several target genes involved in angiogenesis, proliferation, migration and invasion of cancer cells, such as VEGFA, EGFR, c-Myc, Cyclin D1 and MET." (PMID 33088626, 2020).
cancer (continued). "In hepatocellular carcinoma, the NAT MYLK-AS1 can increase EGFR and HER2 expression and subsequently trigger the ERK1/2 signaling pathway, leading to increased cancer cell proliferation." (PMID 32928281, 2020). "Among the seven patients with choroidal metastases in EGFR-mutant NSCLC, six were symptomatic, which was concordant with Shields’ cohort of 420 patients with various primary cancers over a 20-year period, of whom most were symptomatic." (PMID 33272243, 2020). "Nanobody-targeted PDT on co-culture of endothelial and cancer cells showed improved efficacy, when VEGFR2 and EGFR targeting nanobodies were applied simultaneously." (PMID 32977602, 2020). "Triple inhibition with antibody mixtures against EGFR, HER2 and HER3 were effective in blocking the growth of cancer cells in vitro and in vivo." (PMID 33260837, 2020). "Multiple oncogenic signaling including EGFR, CKIT, HER2 receptors via RAS contribute to constitutive activation of NF-κB in cancers." (PMID 32545208, 2020). "The origami-paper-based device, with low cost and low sample consumption, offers an alternative, promising platform for EGFR detection for POCT sensing in early diagnosis and efficacy evaluation of cancer." (PMID 34567646, 2020). "Molecular targeted agents such as cetuximab, an antibody that targets epidermal growth factor receptor (EGFR), have also been shown to increase plasma efficacy when used in combination against cancer cells." (PMID 32033118, 2020). "Alterations in certain other genes, namely EGFR, HER2 and ROS1, were instead only found in patients with cancer." (PMID 32441866, 2020). "Afatinib and Lapatinib are orally administered well tolerated EGFR and HER2 inhibitors in cancer patients." (PMID 35047986, 2020). "However, the precise role of EGFR and ERBBs alone or in crosstalk with other oncoproteins or transmembrane receptors in the development and progression of CC has remained largely unknown and unclear compared with those of other cancer types." (PMID 32708604, 2020). "Inhibition of EGFR’s nuclear import by cetuximab (Erbitux) increases the radiosensitivity of cancer cells by suppressing DNA-PK activity, thereby illustrating the direct regulation of NHEJ-mediated repair by EGFR." (PMID 31948066, 2020). "The abnormal expressions of NOS2, DUOX2/DUOXA2, ESR1, EGFR, MYC, and AKT1, which are being discussed in this study, have been confirmed to be related to cancer." (PMID 33299870, 2020). "Cinobufacin injection plays an important role in the treatment of malignant tumors by regulating the expression of AKT1, VEFG, EGFR, CASP3, and CXCL8." (PMID 32148531, 2020). "EGFR, which can be over-activated through various pathways, regulates the expression of EMT-inducing factors, thereby forming a condition in which cancer can migrate to other tissues." (PMID 32121107, 2020). "Cetuximab bound to EGFR-EVs was co-released from HNC cells, suggesting a mechanism of cancer drug resistance." (PMID 32150875, 2020). "Then, 58 cancer-related targets and 66 KEGG pathways were identified, and PTGS2-, HSP90-, EGFR-, MMP2-, PPARγ-, and GSTP-mediated pathways were predicted to be the antitumor mechanisms of HD-SB." (PMID 32265701, 2020). "A study showed that EGFR translocates to mitochondria in response to stress and TKI treatment in cancer cells." (PMID 31936895, 2020). "More importantly, the hsa05200 pathway derived from both ME and CNV signatures, which includes EGFR, KRAS, MDM2, STAT1 and other signature genes identified by us, is shown to be closely related to initiation and progression of cancer." (PMID 32030321, 2020). "Examples included CCND1 and EGFR, i.e. key regulators of cell cycle progression and PI3K-AKT signaling in a variety of normal and cancer tissues." (PMID 32412911, 2020). "The method was carefully validated with the cancer-related EGF receptor (EGFR) and with cetuximab, used as an EGFR-capturing antibody and as a control of the assay." (PMID 33339292, 2020).
cancer (continued). "Similar to other cancer cell types, inhibition of EGFR activity is a potential drug regimen for SCC, which overexpresses EGFR." (PMID 32093123, 2020). "The Epidermal Growth Factor Receptor (EGFR) appears to play a key role in the development and progression of various cancers, including lung." (PMID 33247670, 2020). "Our objective is to design and evaluate hybridization properties of multiple model helices containing three cancer-related probes, BRAF, KRAS, and EGFR, bound to complementary and mismatched RNA." (PMID 36703315, 2020). "The target of EGF-TiO2 PEG NPs is the epidermal growth factor receptor (EGFR), which is abnormally overexpressed in many cancer types and plays a key role in promoting cell proliferation and opposing apoptosis." (PMID 33003324, 2020). "The binding of HA-MITF was nevertheless enhanced in 4C-HA-MITF cells, with multiple MITFBSs in proximity of several of these cancer-relevant genes (e.g., AXL, IL6, TGFBI, and EGFR,) compared to HA-MITF binding in 3C-HA-MITF." (PMID 32605315, 2020). "EGFR, COX2, MMP-1, and MMP-2 expressed in breast cancers jointly facilitate lung metastasis by promoting the angiogenesis, emancipating cancer cells into the circulation and breaking through lung capillaries." (PMID 33489906, 2020). "METTL3 facilitates the translation of important oncogenes such as epidermal growth factor receptor (EGFR) and tafazzin (TAZ), a Hippo pathway effector, further regulating cancer cell growth, survival, and invasion." (PMID 32709063, 2020). "Another common mutation is T790M in exon 20; it consists of an acquired resistance to EGFR-TKI therapy, bringing to a cancer progression." (PMID 36046486, 2020). "The targets of EGFR and CD3 has been studied for bispecific antibody which crosslinks cytotoxic immune cells to cancer cells induces the immune cells to damage the cancer cells." (PMID 31973200, 2020). "Based on the molecular signatures, modulating EGFR, Ras, Raf, Akt, and VEGF signaling would be a potential strategy in treating this type of cancer." (PMID 32631391, 2020). "Studies have shown involvement of these miRs in key cancer signal transduction pathways: miR-221 in the KRAS pathway, miR -92a in EGFR activation and miR -21 in TGF-β signaling." (PMID 33112562, 2020). "Pathway of pathways in cancer was enriched in 8 DEGs, such as junction plakoglobin (JUP) and epidermal growth factor receptor (EGFR)." (PMID 33178610, 2020). "Results demonstrated that “EGFR tyrosine kinase inhibitor resistance,” “PI3K-Akt signaling pathway,” and “pathways in cancer” were obviously enriched." (PMID 33145355, 2020). "Through this approach, we revealed that downregulated BCKDK inactivated the focal adhesion, ECM-receptor interaction and EGFR (MAPK and PI3K-Akt) signaling pathways, all of which are directly or indirectly related to EMT process in cancer progression." (PMID 32238881, 2020). "The EGFR family-dependent migration of cancer cells induced by CX3CR1 activation is probably a single signaling pathway, since the activation of STAT3 can take place via EGFR/ErbB1." (PMID 32466280, 2020). "Vandetanib is an oral multi-tyrosine kinase inhibitor that targets VEGFR2, epidermal growth factor receptor (EGFR), and RET (rearranged during transfection) pathways in cancer." (PMID 32842503, 2020). "In conclusion, FD extract inhibited the proliferation of the cancer cells by decreasing the expression of CCND1, EGFR, and COX-2." (PMID 32104177, 2020). "Cancer cell reprogramming and phenotypic switches in response to drug exposure has likewise been observed in a subset of NSCLC patients treated with anti-EGFR targeted therapy." (PMID 33297508, 2020). "EGFR activation induces translocation of PKM2 into the nucleus where, in hypoxic human cancer cells, PKM2 physically interacts with and promotes transactivation of HIF-1α." (PMID 32695675, 2020).
cancer (continued). "Combination of MCL-1 inhibitors with inhibitors of EGFR, MEK, or B-RAF showed potent antitumor activity in various preclinical models of cancer." (PMID 32722518, 2020). "Interestingly, the disappearance of RAS mutations in plasma has been reported in some patients with primarily RAS mutant cancers, which raises the question of whether liquid biopsy testing might expand the population of anti-EGFR-eligible patients by including those with primary RAS-mutant mCRC." (PMID 33237900, 2020). "In the course of cancer therapy, MET and EGFR signaling pathways are often targeted either by monoclonal antibodies to prevent binding of activating ligands or by small-molecule inhibitors of receptor phosphorylation." (PMID 32316583, 2020). "Lin and colleagues demonstrated that digoxin, a cardiac glycoside suggested as chemo-therapeutic agent, induced decrease of c-Src, EGFR and STAT3 activation and expression and, consequently, impaired cancer cell proliferation, migration and invasion." (PMID 32517369, 2020). "Inhibition of HER2 pathways by a dual novel EGFR/HER2 inhibitor, KU004, significantly inhibits the Warburg effect by downregulating HK2, thus decreasing cancer cell proliferation." (PMID 33489906, 2020). "Cancer stemness induced via up-regulation of ALDH1A1 and CD44 expression contributes to the acquisition of gefitinib resistance in EGFR-TKI sensitive NSCLC." (PMID 32293355, 2020). "Two clinically proven examples include the Abl, PDGFRβ and Kit inhibitor imatinib and the EGFR/HER2 inhibitor erlotinib, both of which have demonstrated additive anti-cancer effects when used in combination with HDAC inhibitors." (PMID 32987782, 2020). "ROS1-positive cancers show overlapping clinical features with ALK-rearranged NSCLC, although genetic rearrangements in ROS1, EGFR and ALK tend to be mutually exclusive." (PMID 33172113, 2020). "Epidermal growth factor receptor (EGFR) and vascular endothelial growth factor receptor 2 (VEGFR2) play an important role in cancer growth." (PMID 33096664, 2020). "Human epidermal growth factor receptor (HER) 1 and 2, which promote cancer cell growth, survival and migration, are major target molecules for anti-cancer therapies by chemical compounds and monoclonal antibodies (mAbs)." (PMID 32002122, 2020). "Pyrotinib, a novel irreversible HER2/epidermal growth factor receptor (EGFR) dual tyrosine kinase inhibitor, can efficiently inhibit the proliferation of HER2-positive cancer cells in many tumors." (PMID 33194604, 2020). "Clinical trials with EGFR inhibitors and HCC and other cancers have been performed and some are in progress." (PMID 32018226, 2020). "Berberine and Costunolide target different steps of EGFR internalization and degradation, and mutually enhance the inhibition on EGF signaling, resulting in a synergistic anti-cancer effect." (PMID 32298294, 2020). "Among them, genes such as BCL2, CSNK2A1, EGFR, PDGFRA, VEGFA, etc., which have been proved to be targets of anti-cancer drugs, were proposed to provide general administrations for pan-cancers." (PMID 32523951, 2020). "We found that across all three groups 81% of patients with a known molecular target (EGFR, ALK, ROS or BRAF) received a TKI, 91% if considering only those patients who received any cancer specific treatment." (PMID 32470017, 2020). "Targeted demethylation of transcripts coding for oncoproteins such as epidermal growth factor receptor (EGFR) and MYC can suppress proliferation of cancer cells." (PMID 32356894, 2020). "Both the EGFR and FGFR signal transduction pathways are important in cancer, and the FGFR pathway is activated by EGFR-TKI treatment." (PMID 33092268, 2020). "Therefore, EGFR may serve as an attractive target for cancer therapy of different cancers." (PMID 33023595, 2020). "EGFR (epidermal growth factor receptor) and HER2, members of the EGFR family, play critical roles in sustaining cancer cell proliferation, aided by the downstream ERK1/2 signaling pathway." (PMID 32928281, 2020).
cancer (continued). "If it turns out that SCD5 also disrupts signal transmission from EGFR in GBM, this would indicate its anti-cancer properties, since this receptor is essential for the induction of GBM cell proliferation." (PMID 32392704, 2020). "The activity of SCD5 is also correlated with the activity of multiple cancer pathways such as AKT, WNT, and EGFR." (PMID 33029112, 2020). "EGFR is, besides HER3, the preferred heterodimerization partner of HER2, but its role in HER2-overexpressing cancer is still not fully understood." (PMID 33260837, 2020). "Co-culture of M2 macrophages that were polarized from THP1 monocytes with oral cancer or head and neck squamous cancer cells induced the EMT of carcinoma cells through the EGFR pathway and its downstream target ERK in cancer cells." (PMID 32283687, 2020). "This category also includes many known biomarkers for cancer diagnosis or targeted treatment, such as APC Q1291* (for COAD), EGFR L858R (for LUAD), BRAF V600E (for THCA and SKCM), DNMT3A R882H and NPM1 W288Cfs*12 (for LAML)." (PMID 31925297, 2020). "First, XPO1 is frequently overexpressed in human cancers, while XPO1 suppression has been shown to reduce the protein levels of driver oncogenes, such as MYC and EGFR, in multiple cancer types." (PMID 32487143, 2020). "Epidermal growth factor receptor (EGFR) and cyclooxygenase-2 (COX-2) are crucial targetable enzymes in cancer management." (PMID 33171861, 2020). "Since cetuximab and trastuzumab bind to the outer membrane section of EGFR and HER-2 proteins, it is believed that the signaling responses triggered by activation of these two receptors result in apoptosis of cancer cells." (PMID 32401801, 2020). "Growth factor sequestration by IGFBP-3-Fc enhances the activity of EGFR inhibitors by decreasing cell survival and inhibiting bFGF, HGF, and IGF1 growth factor rescue and also potentiates the activity of other cancer drugs." (PMID 32066763, 2020). "In this study, the role of IRX4 in regulating EGFR-TKI resistance and cancer stem-like properties, and the effects of 1,25(OH)2D3 on regulating IRX4-mediated cancer cell stemness and EGFR-TKI resistance, were investigated." (PMID 32820157, 2020). "Together, this suggests that β1-integrin+, EGFR+, Rab13+ sEVs are secreted by KRAS-mutant cancer cells, and that these vesicles play important roles in cancer development and progression." (PMID 32978434, 2020). "It emerges as the effects EGCG on EGFR pathway depend on cancer cell type and suggest as EGCG can have an adjuvant role in EGFR targeted therapy approach." (PMID 31979082, 2020). "In conclusion, EGFR-mediated EV biogenesis seems strictly wedded to the initiation of EMT and cancer progression in various HNC subtypes." (PMID 33302515, 2020). "Osimertinib, which is a third-generation epidermal growth factor tyrosine kinase inhibitor (EGFR-TKI), is an important drug in the treatment of cancer because of its strong anticancer activities and mild adverse effects." (PMID 32764319, 2020). "NRP1 extracellular domain is necessary for EGFR-endocytosis and AKT-dependent cancer cell viability and tumor growth." (PMID 32766254, 2020). "EGFR can activate the RAS/RAF/MEK pathway, which has a central role in the development and progression of cancer." (PMID 32631368, 2020). "Our data demonstrate that PGRMC1 plays a prominent role in regulating the growth of cancer cells by altering the PI3K/AKT/mTOR and EGFR signalling mechanisms in both ER-positive and TNBC cells." (PMID 32704174, 2020). "Considering these findings, and because the EGFR pathway is an important target for anti-cancer drug development, upstream activators of EGFR ligands, namely their sheddases, and regulators of these sheddases, could result in new druggable targets within the EGFR pathway." (PMID 32948029, 2020).